NCOR2 (nuclear receptor corepressor 2)
Diseases named in the same sentence as NCOR2 in open-access papers (continued):
Sharing a sentence is not in itself a finding about the gene and the disease.
cancer (56 papers, 2009 to 2026). A tumor composed of atypical neoplastic, often pleomorphic cells that invade other tissues. "It is evident from the volcano plot that highly mutated genes MUC4, MUC16, CIITA, and ALK are mutated and overexpressed, of which ALK and CIITA are cancer census genes, whereas NCOR2 a transcriptional corepressor was mutated and downregulated." (PMID 37091785, 2023). "Regardless, our results demonstrate that the effect of PLANE on cancer cell proliferation is associated with regulation of the NCOR2-202-generating AS event." (PMID 34145290, 2021). "Abnormal expression of NCOR2 is associated with certain cancers." (PMID 32508530, 2020). "Taking into consideration the association between NCoR2, PXR and cancer malignancy, we evaluated whether NCoR2 can indeed alter cell growth in HNSCC." (PMID 29470550, 2018). "The AML also lost mutations in cancer genes toward the end of treatment in comparison with initiation, e.g., in IL3 (p.P27S, VAF 9.3%) and NCOR2 (p.G1830delinsSSGG, VAF 19.6%)." (PMID 38012682, 2023). "As a transcription co-regulator of metabolic processes, NCOR2 is involved in the development of various cancer entities by unbalancing pro- and anti-inflammatory signaling pathways." (PMID 37131060, 2023). "For example, the lncRNA PLANE (Pan-cancer lncRNA activating NCOR2 responsive to E2F1) is generally upregulated in multiple cancer types via genomic amplification and E2F1-mediated transcriptional activation." (PMID 35427215, 2022). "Consistent with these cancer-promoting actions, our results showed that hnRNPM along with PLANE represses the AS event generating NCOR2-202 and thus promotes cancer cell proliferation." (PMID 34145290, 2021). "Of note, cancer cells often display altered expression of NCOR2, implicating a role of its deregulation in cancer pathogenesis." (PMID 34145290, 2021). "The resulting downregulation of NCOR2 at the protein level contributes to the increased proliferation and tumorigenicity of cancer cells." (PMID 34145290, 2021). "NCOR2 is a nuclear receptor co-repressor (NCOR) targeting various cancer-related transcription factors." (PMID 34864816, 2021). "Our study provides the first small molecule against NCOR2, providing a small molecular drug for NCOR2-related pathologies, including cancer." (PMID 32550907, 2020). "For example, the expression of corepressors such as NCOR1 and NCOR2/SMRT determine how several cancers respond to nutritive ligands." (PMID 31683867, 2019). "Our data as well as previous studies, although remarking the NCoR2 importance in cancer growth, evidence differential NCoR2 effects in different models." (PMID 29470550, 2018). "In particular, BeME-WithFun identified functionally coherent modules containing cancer associated genes, including previously unappreciated modules such as the NCOA3/NCOR2 module." (PMID 29023534, 2017). "NCoR2 is a corepressor that targets various TFs involved in cancer growth and development." (PMID 37450923, 2024). "Overall the genomic landscape was stable, with pathogenic or likely pathogenic alterations being identified in 51 cancer genes, with 9 (18%) of them showing alterations being recurrent across different samples (MYCN, CDKN2A/2B, CDK4, GLI1, AKT1, IGF2, MED12, NCOR2)." (PMID 37730754, 2023). "The inhibitory or oncogenic effects of NCOR2 show heterogeneity among different types of cancer." (PMID 36497280, 2022). "Nonetheless, whether each of the other NCOR2 isoforms has any specific effect on cancer pathogenesis remains to be defined." (PMID 34145290, 2021). "In the unclassified subgroup, apart from previously reported mutations in epigenetic regulators in multiple cancers, including KMT2C, KMT2D, KMT2B, PRDM2, NCOR2, KAT6B, and EP300, in this cohort, we also found new recurrent mutations in epigenetic regulators, including CREBBP and PRDM16." (PMID 30950204, 2019).
cancer (continued). "In the absence of agonist, LXRA but not LXRB, is primarily repressed by corepressors NCOR1 and NCOR2/SMRT and previous reports demonstrate elevated corepressor expression helps prostate and bladder cancer cells to evade anti-proliferative actions of NRs through compromising the ligand response." (PMID 31683867, 2019). "PXR and NCoR2 have been reported to modulate malignancy of cancer types other than HNSCC." (PMID 29470550, 2018). "Notably, the RXRA protein was in protein complexes with RARA, PPARG, NCOA1, NCOA2, and NCOR2 cancer drivers." (PMID 29572294, 2018). "Interestingly, module 7 contains two genes with co-occurring mutations: NCOR2 (nuclear co-repressor) and NCOA3 (coactivator), with the latter being a well-known cancer driver." (PMID 29023534, 2017). "In conclusion, NCOR2 may be an important inhibitor of cancer occurrence or development." (PMID 32508530, 2020). "HIOTs were also found in another two cancer genes BCOR (intron) and NCOR2 (intron) by RGN11155 and RGN11189 respectively." (PMID 35831290, 2022). "Analysis of the site of expression revealed the existence of AKT1, MTDH, and NCOR2 genes in the colorectum and presence of TGFBR1 and MTDH in various cancer cell lines such as A-549 and HeLa." (PMID 36499586, 2022). "Functionally, NCOR2 forms a large corepressor complex that contains SI3A/B and histone deacetylases HDAC members, and modulates homeostasis and cancer development." (PMID 35646694, 2022). "We identified 14 cancer driver genes, including the most frequently altered KMT2C (100%), KNL1 (100%), NCOR2 (100%), and CCDC6 (93%) genes." (PMID 34245124, 2021). "Both NCOR2 and CTBP2 were hypermethylated in liver and blood of WD patients and function as transcriptional co-repressors that are dysregulated in cancer." (PMID 30709419, 2019). "We also confirmed the cancer promoting role of very rare helpers, including ABI2, NCOR2 and PAK1 that are altered in 1–4% of EACs." (PMID 31308377, 2019). "Regardless, that PLANE links hnRNPM to repression of the NCOR2-202-generating AS is not in dispute since the process can be modelled in vitro and the action is sufficient to suppress cancer cell survival tumorigenicity." (PMID 34145290, 2021). "Reducing NCOR2 expression or preventing its interaction with Histone Deacetylase, HDAC3, enhances innate immune cell recruitment and activity, and elevates MHC class I levels on disseminated cancer cells to potentiate CD8+ T cell activity and apoptosis induction that prevents metastatic progression." (PMID 42086546, 2026). "The precise molecular mechanisms underlying HDAC4's role in cancer remain incompletely understood, but it may involve interactions with the corepressor complex NCOR1/NCOR2/HDAC3 and influence the transcription landscape of cancer cells through epigenomic reprogramming." (PMID 38911380, 2024). "In addition, we also found that a set of 730 CpG sites located within the epi-driver genes had the same direction of change for three or more cancer subtypes, including genes that had previously proved to have biological functions in cancer progression such as EGFR, NCOR2, MAML3, TSC2, and FGFR2." (PMID 35069697, 2021). "To examine whether in cancer cells, the corepressor complex could mediate the activation function of REV-ERBα, we knocked down NCoR1 and NCoR2 and found that their knockdown did not cause any significant effect on the expression of REV-ERBα activated genes in PI3K and MAPK signaling programs." (PMID 39383000, 2024). "Researchers had identified ZNF703 as a cofactor of a nuclear complex covering DCAF7, PHB2 and NCOR2 through mass spectrometry and pointed out that ZNF703 expression could result in the activation of stem cell-related gene expression leading to an increase in cancer stem cells." (PMID 27764785, 2016).
cancer (continued). "In summary, except for CDKN2A, which is a clear outlier in the dataset under consideration, the changes in the local number of CNVs did not appear to be connected to the pan-cancer genes located in these regions (CAMTA1 and MTOR, MUC4 and TFRC, and NCOR2)." (PMID 31783642, 2019).
infection (3 papers, 2016 to 2025). The state of being infected such as from the introduction of a foreign agent such as serum, vaccine, antigenic substance or organism. "The RT-qPCR results confirmed that the NCOR2-013 isoforms increased 2-fold at the mRNA level in T. marneffei-infected THP-1 macrophages at 24 h post-infection." (PMID 37845378, 2023). "Moreover, at 24 h post infection, the expression of NCOR2-013 isoforms was significantly increased in the T. marneffei-infected TUT1-overexpressing THP-1 macrophages, but significantly decreased in the T. marneffei-infected TUT1-knockdown THP-1 macrophages." (PMID 37845378, 2023). "To explore the molecular mechanism of NCOR2-013 inhibiting the inflammatory response, we performed RNA-seq analysis on T. marneffei-infected NCOR2-013 overexpressing macrophages and control cells at 24 h post-infection." (PMID 37845378, 2023). "To determine whether the effect on NCOR2 AS was mediated by direct binding of TUT1, we performed RIP assay in T. marneffei-infected TUT1-overexpressing THP-1 macrophages at 24 h post-infection, and found that TUT1 binds to NCOR2 pre-mRNA." (PMID 37845378, 2023). "Notably, although NcoR2 and HDAC3 remained at a high level over the infection period, they failed to reside on IRF7 promoter and hinder its transcription when Bcl6 expression was suppressed by miR-127." (PMID 26728228, 2016).
metabolic disease (3 papers, 2019 to 2023). A congenital disorder (due to inherited enzyme abnormality) or acquired (due to failure of a metabolically important organ) disorder resulting from an abnormal metabolic process. "In conclusion, HDAC3, NCoR1, and NCoR2 play a major role in regulating metabolism and have been implicated in several metabolic diseases." (PMID 37674539, 2023).
kidney disease (1 paper, 2025). "When referenced against published findings in the GWAS and EWAS catalog, NCOR2, a nuclear receptor coregulator, has repeatedly been associated with kidney disease." (PMID 39448372, 2025). "Overall, NCOR2 and FRMD4A were consistently reported to be associated with kidney disease when referenced against the GWAS and EWAS catalogs." (PMID 39448372, 2025).
NCOR2 also shares sentences with these, for which no sentence is quoted: atherosclerosis (3 papers); Rett syndrome (3); clubfoot (2); colon cancer (2); esophageal squamous cell carcinoma (2); Hepatic steatosis (2); ovarian serous cystadenocarcinoma (2); soft tissue neoplasm (2); adrenocortical carcinoma (1); agammaglobulinemia (1); AIDS (1); anaplastic large cell lymphoma (1); anemia (1); asthma (1); Ataxia (1); B-cell lymphoma (1); bladder urothelial carcinoma (1); cardiovascular disease (1); cervical squamous cell carcinoma (1); colorectal adenocarcinoma (1); diffuse large B-cell lymphoma (1); embryonal rhabdomyosarcoma (1); endocervical adenocarcinoma (1); endometrial cancer (1); epithelioid sarcoma (1); germ cell tumor (1); granulosa cell tumors of the ovary (1); hearing loss (1); Hyperglycemia (1); hyperlipidemia (1).
A further 23 diseases each share a sentence with NCOR2 in 1 paper.